VIM (vimentin)
Diseases named in the same sentence as VIM in open-access papers (continued):
Sharing a sentence is not in itself a finding about the gene and the disease.
tumor (continued). "Moreover, Vimentin plays a crucial role in maintaining the cytoskeletal architecture, and it is able to mediate the microtubule polarity organization, thus inducing tumor cell malignancy." (PMID 32143529, 2020). "However, other studies indicate that a high expression of vimentin is associated with a poor prognosis in other cancer types, with the information on the expression of vimentin by tumor cells and prognosis in OC being scarce." (PMID 32731632, 2020). "IHC results showed that the protein level of E‐cadherin increased, whereas protein levels of p‐STAT3 (Tyr705), N‐cadherin, and vimentin decreased in the tumor tissues grown from HeLa cells in the RES pretreatment and treatment groups, compared to those in the respective control groups." (PMID 33040485, 2020). "Moreover, immunohistochemistry was conducted to analyze CSCs markers (CD44 and CD24) and EMT markers (E-cadherin, β-catenin, vimentin, and N-cadherin) in benign breast lesions (control), paracancer tissues, and tumor tissues." (PMID 33282946, 2020). "Furthermore, in LK0902 and LK0917 cells, increased VIM mRNA expression was observed in tumor cells from tumor/CAF spheroids." (PMID 33353547, 2020). "Furthermore, western blot results indicated that β-catenin, P-AKT,P-GSK-3β, Cyclin D1, Vimentin, and Bcl-2 protein expression in xenograft tumor were obviously reduced in SC66 treatment group." (PMID 32848734, 2020). "On IHC, tumour cells were positive for vimentin, cytokeratin, and CD99." (PMID 33520482, 2020). "Osthole (100, 150, and 200 μm) could downregulate the protein expression of MMP-9 and vimentin to suppress TGF-β dependent tumor invasion." (PMID 32028721, 2020). "Moreover, we performed IHC staining CD44s, E-cadherin, Vimentin, and caspase-1 in tumor tissues obtained from the corresponding group of nude mice." (PMID 33168816, 2020). "We and others have extensively reported vimentin expression in tumor cells of epithelial origin in vitro, in animal models, in a large variety of epithelial human tumors and CTCs isolated from cancer patients in which it associates with poor clinical parameters." (PMID 32152404, 2020). "Additionally, IHC staining results showed a higher expression of E-Cadherin and lower expression of Vimentin in shSPOCK1 group tumor tissue." (PMID 33293473, 2020). "In this study, we proposed radiomics features and the binary logistic regression model to identify the immunohistochemical typing of Ki-67, S-100, CD34 and vimentin, so as to achieve the image-indication of tumor progression, angiogenesis, proliferation or invasion." (PMID 31968004, 2020). "Notably, we demonstrated that either low miR-146a or high vimentin expression was significantly correlated with tumor formation, tumor stages and poor overall survival rate of ESCC patients." (PMID 33248456, 2020). "It should also be emphasized that during EMT tumor cells significantly modify the cytoskeletal structure with an increase in the expression of vimentin, critically involved in the adoption of a mesenchymal form and in increased motility, for this reason it is considered the main marker of EMT." (PMID 33396625, 2020). "Indeed, vimentin is widely used as a canonical marker of EMT reprogramming, associated with the acquisition of a migratory and invasive tumor cell phenotype." (PMID 31940801, 2020). "Immunohistochemistry showed that the tumor cells were positive for vimentin." (PMID 32299394, 2020). "Besides, HBx can also downregulate tumor suppressive lncRNA Dreh, leading to re-expression of vimentin and promoting HCC metastasis." (PMID 32295598, 2020). "Interestingly, FOLFIRINOX-treated primary tumors appeared even more de-differentiated, as illustrated by the presence of more vimentin-positive tumor cells." (PMID 32948057, 2020). "Many studies have confirmed that E2F1 could activate the expression of stromal markers related to EMT such as vimentin and fibronectin and facilitate the pathogenesis processes such as fibrosis and tumor progression." (PMID 32596346, 2020).
tumor (continued). "Epithelial to mesenchymal transition (EMT), characterized by the loss of epithelial characteristic (E-cadherin expression), and acquisition of a mesenchymal phenotype (N-cadherin and vimentin expression) is a key step contributing cancer progression by directly inducing tumor invasion." (PMID 32443471, 2020). "Cytokeratin/vimentin co-expression in tumor cells indicates partial EMT." (PMID 32630033, 2020). "These tumours also exhibited an increase in E-cadherin expression and a reduction in Vimentin expression in xenografts derived from PinX1 overexpression nasopharyngeal CD133+ CSCs, while the expression levels were reversed by co-inhibition of miR-200b via immunohistochemistry." (PMID 32028978, 2020). "Immunohistochemically, the tumor showed immunoreactivity for vimentin and S100." (PMID 34277484, 2020). "EMT upregulation in HNC tumor tissues was best quantified using vimentin/cytokeratin index ratio." (PMID 32630033, 2020). "The mesenchymal marker Vimentin expression was significantly higher in tumor sections of nude mice receiving control shRNA treated cells followed by LPA treatments than the RAGE silenced cells injected nude mice tumor sections confirming epithelial to mesenchymal transition through RAGE." (PMID 33109194, 2020). "Moreover, another key mesenchymal mark vimentin can interact with lncRNA Dreh, which functions as a tumor suppressor in HCC." (PMID 32295598, 2020). "For example, the center of the tumor and the invasive border may have a different level of vimentin expression." (PMID 32850341, 2020). "Eighty-four tumor tissues were used to detect the expression of IL-8, snail, and vimentin." (PMID 32471980, 2020). "Cytoplasmic VIM translocated to the tumor CSV has been reported by several previous publications." (PMID 31981446, 2020). "Previously, many kinds of tumor cells have been reported to express vimentin on their surface." (PMID 32645972, 2020). "Therefore, vimentin is a well-established canonical marker of EMT reprogramming, associated with the acquisition of a migratory and invasive tumor cell phenotype, with an early overexpression during the transition." (PMID 32933173, 2020). "Finally, Vimentin staining in these tumor cells suggested epithelial-to-mesenchymal transition (EMT)." (PMID 32093026, 2020). "Probably the most thoroughly investigated drug targeting vimentin IFs is the tumor inhibitor Withaferin A (WFA), derived from the plant Withania somnifera, which was found to target and directly bind vimentin in an effort to find the mode of action related to its antiangiogenic properties." (PMID 31940801, 2020). "Furthermore, EMT was dramatically repressed in the shGDF15-expressing tumors, in which expression levels of N-Cadherin and Vimentin were obviously reduced, implicating the repression of tumor metastasis after GDF15 abrogation." (PMID 32076610, 2020). "Indeed, we found that downregulation of miR-146a led to upregulation of vimentin thereby promoting cell proliferation, colony and tumor formation as well as cell motility of ESCC cells that highly assemble FN on the cell membrane." (PMID 33248456, 2020). "Almost 3% of HNC tumor cells were cytokeratin/vimentin double positive." (PMID 32630033, 2020). "PLCɛ could induce the alterations of E-cadherin, Vimentin and N-cadherin toward a phenotype favoring tumor metastasis." (PMID 32879302, 2020). "First, we removed blood‐derived cells, such as red blood cells and white blood cells, by centrifugation and phase‐enrichment to achieve high CTC enrichment efficiency, and then we employed the iFISH platform, which combines immunofluorescence staining of tumor proteins (vimentin)." (PMID 32659050, 2020). "Studies on stem cells have shown vimentin to be important for tumor growth." (PMID 32670437, 2020). "High vimentin expression was accompanied by high PD-1, PD-L1 expression, and increased regulatory T cell infiltration (all P < 0.001), indicating immunosuppression in the tumor microenvironment." (PMID 32850341, 2020).
tumor (continued). "For E-cadherin, claudin-1, vimentin, and nuclear Snail/Slug expression, these differences occurred in both the tumor center and the tumor margin, whereas significantly higher levels in surgically resected samples were observed only at the tumor margin for ZEB1." (PMID 32093260, 2020). "Immunohistochemically, the tumor cells were positive for vimentin, epithelial membrane antigen, calponin, and were partially mild to moderate positive for estrogen receptor, but completely negative for S100 protein, glial fibrillary acidic protein, CD34, desmin, SMA and cytokeratin." (PMID 31915021, 2020). "To clarify the mechanism underlying EVI5-mediated tumor metastasis, we analyzed the molecular expression of TGF-β receptor II, TGF-β receptor I, p-Smad3, Snail, Vimentin, MMP2 and N-Cadherin levels were significantly decreased and E-Cadherin was significantly increased in EVI5-knockdown cells." (PMID 32393392, 2020). "For evaluating the correlation of Vimentin and E-cadherin expression with sex, age, the primary site of cancer, tumor stage, grade of cancer, pT category (primary tumor) and pN Category (regional lymph nodes) and also vascular invasion were used for statistical tests." (PMID 32665775, 2020). "Interestingly, the upregulation of vimentin increased at the periphery of the tumor cell community after CAF-CM treatment, while cells in the center exhibited greater E-cadherin retention." (PMID 33204333, 2020). "Moreover, indicating epithelial-mesenchymal transition (EMT), vimentin occurred in the cytoplasm of several tumor cells." (PMID 32388727, 2020). "Besides E-cad, activation of the transcription factor SNAI2 and increased expression of vimentin (VIM) have also been found to act as critical factors in implicating EMT during tumor progression." (PMID 32483426, 2020). "On IHC, tumour cells were positive for vimentin, cytokeratin and CD34." (PMID 33520482, 2020). "Tumor cells stain positive for vimentin, S-100 protein, and SOX10; neuroendocrine markers such as CD56, synaptophysin, and NSE may also be positive." (PMID 33025168, 2020). "CircHIPK3 promoted tumor growth, proliferation and metastasis and inhibited apoptosis of RC cells by inhibiting the expressions of C caspase-3, Bax and E-Cad and promoting the expressions of Bcl-2, N-Cad, Vimentin and Ki-67." (PMID 32550826, 2020). "High vimentin expression may also induce increased PD-L1 expression both in tumor and stromal cells." (PMID 32850341, 2020). "In addition, our results support a functional role of this vimentin/TF regulatory axis in providing tumor cells with enhanced coagulant activity and increased metastatic colonization abilities." (PMID 32152404, 2020). "(D) The relative mRNA expression of N-cad (Exo-3B, P = 0.0287; Exo-3B-KD, P = 0.0014), Snai1 (Exo-3B, P = 0.0004; Exo-3B-KD, P = 0.0014), β-catenin (Exo-3B, P < 0.0001; Exo-3B-KD, P = 0.0166) and Vimentin (Exo-3B, P = 0.0003; Exo-3B-KD, P = 0.0139) in ECs treated with exosomes from tumor cells." (PMID 31477130, 2019). "In the EMT process of tumor cells, expression of proteins promoting cell-cell contact such as E-cadherin is decreased, while expression of mesenchymal markers such as vimentin, MMP-2 and -9 is increased, resulting in cell migration and invasion ability is enhanced." (PMID 30862004, 2019). "Moreover, the immunohistochemical analyses in our mice xenograft tumor models showed the intense Ki-67, Snail and Vimentin staining at the edge of tumors, a region where tumor cells were considered to have higher growth and invasive potential." (PMID 31659158, 2019). "Moreover, we noted strong nuclear translocation of β-catenin and perinuclear condensation of vimentin, which is another hallmark of EMT, in the Treg-co-cultured B16-BL6 tumor tissues." (PMID 31690033, 2019). "Moreover, the resected tissues from the treated xenograft tumours were analysed by IHC to confirm the expression of PD-L1, E-cadherin and vimentin." (PMID 31331328, 2019).
tumor (continued). "Vimentin has been shown to be required for tumor metastasis in a number of animal studies." (PMID 31126068, 2019). "This complex formation involving IF proteins is critical for inhibiting autophagy while facilitating tumor cell growth, as shRNA-mediated suppression of vimentin expression increased autophagy while decreasing Akt-mediated tumor cell growth in rat2 fibroblasts." (PMID 31126068, 2019). "A decrease of epidermal E‐cadherin (CDH1) and a concomitant increase of vimentin (VIM) expression in the dermis indicate an enhanced tumor invasiveness, which might refer to epithelial–mesenchymal transition (EMT)." (PMID 31580518, 2019). "Furthermore, PDAC patients with tumour cells that express decreased E-cadherin and higher amounts of vimentin, s100A4, fibronectin and SNAI1 are more likely to have distant metastases, lymph node invasion and lower overall survival." (PMID 31703358, 2019). "Tumor cells were positive for vimentin, ER, PgR, and desmin." (PMID 31240143, 2019). "For both cell line and tumor pieces, evaluation of gene expression demonstrates high endogenous expression of select mesenchymal genes (VIM, cMYC, FRA1, SNAI1 and SLUG), and low endogenous expressions of epithelial gene CD24 and mesenchymal genes TWIST and ZEB1." (PMID 30845999, 2019). "Furthermore, vimentin was observed in a wide range of cancer types and seems to correlate with tumor aggressiveness and poor prognosis." (PMID 31242696, 2019). "Moreover, western blot analysis and RT-PCR revealed that PTPRB knockdown decreased vimentin expression and increased E-cadherin expression in tumor tissues." (PMID 31040266, 2019). "(C) Vimentin expression in human lung tumor tissues and non-tumor tissues." (PMID 31420013, 2019). "Moreover, tumor sections from PTPRB knockdown xenografts showed lower levels of vimentin expression and upregulation of E-cadherin expression." (PMID 31040266, 2019). "Epithelial-mesenchymal transition (EMT), which is characterized by the loss of the epithelial marker E-cadherin and the gain of the mesenchymal marker vimentin, plays important roles in tumour progression, including intravasation, metastasis and resistance to therapy." (PMID 31196220, 2019). "We tested protein expression of epithelial and mesenchymal cell lineages and found that while the 927 tumor resection was highly positive for e-cadherin expression, cell lines derived from the resection were highly vimentin positive with undetectable e-cadherin expression." (PMID 30862796, 2019). "In the coculture model to induce EMT in JM1 cells, WB analysis found upregulated HER2 expression along with downregulated E‐cadherin and upregulated Vimentin, especially in the JM1/6+ cells, indicating that regulation of HER2 may be associated with tumor EMT." (PMID 30714677, 2019). "IFNα-2b inhibited migration of tumor cells to the suspension fraction and promoted an increase in expression of CK and EpCAM in 2D and 3D cell cultures, but only in the 3D culture was expression of vimentin increased." (PMID 30930631, 2019). "While evident in both GBM and the GS tumours, this observation was most marked in GS and is consistent with disease biology, where the vimentin+ MES-like (sarcomatous) tumour cells are highly motile and migrate to BM-rich regions in the brain such as the leptomeninges." (PMID 31463571, 2019). "In addition to a high percentage of VIM-positive tumour cells, MSCCs had a low percentage of CDH1-positive cells and a high percentage of TWIST1-, ZEB1- and ZEB2-positive cells, characteristic of EMT." (PMID 31080552, 2019). "Furthermore, expression of Vimentin was decreased in RNF208-ovexexpressing primary tumor tissues compared with control tissues in xenograft mouse experiment." (PMID 31862882, 2019). "High vimentin expression correlates with increased tumor growth, invasion, and poor prognosis." (PMID 31534628, 2019).
tumor (continued). "Furthermore, vimentin is a marker of epithelial-mesenchymal transition, a process by which tumor epithelial cells acquire the ability to migrate, and is involved in cell invasion and metastasis." (PMID 31534630, 2019). "The ZJU-0430 cell line and the original tumour were staining for CK-pan, vimentin, CK7, and CK19." (PMID 31367188, 2019). "For example, while some CTCs from these PDOX tumor models showed high expression of the epithelial marker cytokeratin or the mesenchymal marker vimentin, many CTCs stained strongly for both cytokeratin and vimentin." (PMID 31462307, 2019). "Wondering whether KK‐LC‐1 was associated with EMT markers in HCC in vivo, we performed E‐cadherin and vimentin immunostaining analysis on tumours derived from xenograft mice models." (PMID 30895661, 2019). "At the core of tumor, when cancer cells are undergoing EMT, epithelial cells gain a mesenchymal phenotype (e.g., loss of E-cadherin, cytokeratin, and claudin while acquiring N-cadherin and vimentin)." (PMID 31394796, 2019). "However, remodelin attenuated the doxorubicin-induced EMT in tumor cells, as confirmed by upregulation of E-cadherin and downregulation of vimentin." (PMID 31354912, 2019). "Finally, we observed an increase in vimentin expression in HK-2 (non-tumor cell) incubated with hRAT-CMs compared to hRAN- and control-CMs (p < 0.001)." (PMID 31534630, 2019). "(D) The mRNA expression of N-cad (Exo-3B, P < 0.0001; Exo-3B-KD, P = 0.0015), Snai1 (Exo-3B, P = 0.0011; Exo-3B-KD, P = 0.0010), β-catenin (Exo-3B, P = 0.0015; Exo-3B-KD, P = 0.1158) and Vimentin (Exo-3B, P = 0.1211; Exo-3B-KD, P = 0.7113) in tumor cells, which were treated with exosomes." (PMID 31477130, 2019). "We investigated the expression of the typical epithelial cell adhesion molecule N‐cadherin and E‐cadherin and mesenchymal marker vimentin to determine whether EMT occurs during tumor growth and compared the results with RGS5 expression at the same sites." (PMID 31049219, 2019). "Furthermore, the CP466722 treatment significantly increased expression of E-cad and decreased the expression of N-cad, Vimentin and Snail in the A549cisR cell-derived xenograft tumor." (PMID 30961670, 2019). "In addition, Notch1 can reduce the expression of zinc finger E-box binding homeobox (ZEB) and vimentin by regulating miR-200b, thereby promoting tumor cell EMT." (PMID 30622441, 2019). "Finally, in-brain slices, the percentage of tumor cells found to be positive for the expression of the mesenchymal marker vimentin, was still reduced in mice treated with SAFit2." (PMID 31583120, 2019). "Second, vimentin, which is a major constituent of the intermediate filament family of proteins that maintains cellular integrity and provides resistance against stress, has been shown to accelerate tumour growth and invasion." (PMID 31423109, 2019). "During tumor development and progression extracellular vimentin may be a target of PTMs such as proteolytic cleavage by matrix metalloproteases (MMPs) overexpressed in the tumor microenvironment as well as citrullinations." (PMID 31827725, 2019). "Moreover, knockdown of MIR4435-2HG increased E-cadherin and decreased N-cadherin, vimentin, c-Myc, β-catenin, cyclin D1 and survivin expression in tumor xenografts." (PMID 31484163, 2019). "The morphology of daughter cells was similar to parental tumor, indeed they expressed cytokeratin, vimentin, estrogen receptor-α (ERα), and PgR suggesting that a small population of cells is able to maintain features of parental tumor and to differentiate in vivo." (PMID 31752447, 2019). "In addition, miR-7-5p significantly suppressed the EMT in A549 xenografts, as indicated by the downregulation of N-cadherin and vimentin and upregulation of E-cadherin at the mRNA level in the tumor." (PMID 31832068, 2019).